Y_RNA (Y RNA )
Gene: Miscellaneous RNA gene on chromosome 6 (128,761,717 to 128,761,808, reverse strand). Ensembl gene ENSG00000202200.
Homologues: Orthologues: chimpanzee Y_RNA (100% identical), guinea pig Y_RNA (84% identical), dog Y_RNA (83% identical), pig Y_RNA (79% identical). Paralogues in human: RNY3 (84% identical), Y_RNA (84% identical), Y_RNA (83% identical), RNY3P1 (82% identical), Y_RNA (82% identical), RNY3P4 (80% identical), Y_RNA (80% identical), RNY3P16 (79% identical), Y_RNA (79% identical), Y_RNA (78% identical), RNY3P14 (77% identical), Y_RNA (77% identical), and 93 more.